FAM186A (family with sequence similarity 186 member A)
Synonyms: LOC121006
Tractability: Antibody: the Human Protein Atlas places it where antibodies can reach. PROTAC: ubiquitination databases record sites on it.
Gene: Protein-coding gene on chromosome 12 (50,326,230 to 50,396,622, reverse strand). Ensembl gene ENSG00000185958.
Subcellular location (Human Protein Atlas): Nucleoplasm; Vesicles; Plasma membrane
Genetic constraint (gnomAD): Loss-of-function variants: 161 observed, 215.27 expected, observed/expected ratio (o/e) 0.75, 90% interval 0.66 to 0.85. The synonymous counts are far from expectation, so gnomAD's model fits this gene poorly and the ratio says little. Missense variants: 2,166 observed, 2,738 expected, observed/expected ratio (o/e) 0.79, 90% interval 0.76 to 0.82. Synonymous variants: 798 observed, 1,000.4 expected, observed/expected ratio (o/e) 0.8, 90% interval 0.75 to 0.85.
Homologues: Orthologues: mouse Fam186a (42% identical).
Diseases named in the same sentence as FAM186A in open-access papers:
FAM186A is named in the same sentence as 4 diseases in open-access papers, as found by Europe PMC text mining. Sharing a sentence is not in itself a finding about the gene and the disease. The quoted sentences say what the papers report.
atherosclerosis (1 paper, 2022). A disease characterized by the build-up of fatty material and calcium deposition in the arterial wall resulting in partial or complete occlusion of the arterial lumen. "Endou, Hdac7, Senp1, Olfr286, Olfr285, Nckap5l, Smarcd1, Lima1, Fam186a, and Espl1 are probable candidate genes for distal Chr15 atherosclerosis QTL (Ath53)." (PMID 36078077, 2022).
cystic teratomas of the ovary (1 paper, 2022). "Among the 15 prevalent mutated genes, 8 with different variants in exons with changes in protein coding are important for the development of mature cystic teratomas of the ovary: FLG, MUC17, MUC5B, RP1L1, NBPF1, SLC29A3, SGK223, and FAM186A." (PMID 36289533, 2022).
tumor (1 paper, 2015). "We further explored if rs1129406 (ATF1, 12q13), rs12303082 (FAM186A, 12q13), rs6580742 (FAM186A, 12q13), rs16888728 (UTP23, 8q24) and rs3184504 (SH2B3, 12q24) genotypes affect the CRC risk differentially by sex, age at diagnosis, tumor site, stage and MSI status." (PMID 26553438, 2015).
FAM186A also shares sentences with these, for which no sentence is quoted: cancer (1 paper).